ZNF26 (zinc finger protein 26)
Description:
May be involved in transcriptional regulation.
Synonyms: KOX20; FLJ20755; HEL-179
Tractability: PROTAC: ubiquitination databases record sites on it.
Gene: Protein-coding gene on chromosome 12 (132,986,365 to 133,032,952, forward strand). Ensembl gene ENSG00000198393.
Subcellular location: Nucleus
Subcellular location (Human Protein Atlas): Mitochondria; Nuclear bodies
Pathways (Reactome):
Gene expression (Transcription): Generic Transcription Pathway
Gene Ontology:
Molecular function: protein binding
Biological process: regulation of DNA-templated transcription
Cellular component: nucleus
Genetic constraint (gnomAD): Loss-of-function variants: 32 observed, 55.08 expected, observed/expected ratio (o/e) 0.58, 90% interval 0.44 to 0.78. The upper end of that interval is the gene's LOEUF score, 0.78, which puts it in group 3 of 6, group 1 being the genes least tolerant of losing a copy. Missense variants: 523 observed, 660.52 expected, observed/expected ratio (o/e) 0.79, 90% interval 0.74 to 0.85. Synonymous variants: 221 observed, 219.52 expected, observed/expected ratio (o/e) 1.01, 90% interval 0.9 to 1.12.
Homologues: Orthologues: chimpanzee ZNF26 (98% identical), macaque ZNF26 (97% identical), pig ZNF26 (92% identical), rabbit ZNF26 (91% identical), dog ZNF26 (90% identical). Paralogues in human: ZNF484 (51% identical), ZNF182 (51% identical), ZNF41 (50% identical), ZNF300 (50% identical), ZNF33B (49% identical), ZNF605 (49% identical), ZNF717 (49% identical), ZNF334 (48% identical), ZNF630 (48% identical), ZNF658 (48% identical), ZNF585B (47% identical), ZNF568 (47% identical), and 164 more.
Diseases named in the same sentence as ZNF26 in open-access papers:
ZNF26 is named in the same sentence as 4 diseases in open-access papers, as found by Europe PMC text mining. Sharing a sentence is not in itself a finding about the gene and the disease. The quoted sentences say what the papers report.
colorectal cancer (1 paper, 2021). A primary or metastatic malignant neoplasm that affects the colon or rectum. "The mRNA expression of ZNF26 in colorectal cancer cell lines was detected by qRT-PCR." (PMID 34178996, 2021). "Hence, we tested the hypothesis that, as a novel biomarker, ZNF26 might be potentially valuable in the diagnosis and prognostic evaluation for colorectal cancer." (PMID 34178996, 2021). "Therefore, as a novel biomarker, ZNF26 may be a promising candidate in the diagnosis and prognostic evaluation of colorectal cancer." (PMID 34178996, 2021).
ZNF26 also shares sentences with these, for which no sentence is quoted: Alzheimer disease (1 paper); cardiovascular disease (1); Huntington disease (1).